Y_RNA (Y RNA )
Gene: Miscellaneous RNA gene on chromosome 16 (47,313,027 to 47,313,121, reverse strand). Ensembl gene ENSG00000222767.
Homologues: Orthologues: chimpanzee Y_RNA (96% identical), macaque Y_RNA (87% identical). Paralogues in human: Y_RNA (84% identical), Y_RNA (83% identical), Y_RNA (82% identical), RNY3 (81% identical), Y_RNA (81% identical), RNY3P1 (80% identical), Y_RNA (80% identical), Y_RNA (79% identical), RNY3P14 (78% identical), RNY3P5 (78% identical), Y_RNA (78% identical), RNY3P16 (77% identical), and 93 more.